RNU6-1163P (RNA, U6 small nuclear 1163, pseudogene)
Gene: Small nuclear RNA gene on chromosome 6 (112,971,493 to 112,971,599, forward strand). Ensembl gene ENSG00000201386.
Homologues: Orthologues: chimpanzee U6 (100% identical), macaque U6 (81% identical), mouse Gm25705 (75% identical). Paralogues in human: RNU6-45P (85% identical), RNU6-19P (84% identical), RNU6-31P (84% identical), RNU6-35P (84% identical), RNU6-12P (83% identical), RNU6-13P (83% identical), RNU6-21P (83% identical), RNU6-24P (83% identical), RNU6-25P (83% identical), RNU6-32P (83% identical), RNU6-41P (83% identical), RNU6-49P (83% identical), and 1284 more.